RN7SKP36 (RN7SK pseudogene 36)
Gene: Miscellaneous RNA gene on chromosome 4 (7,112,088 to 7,112,399, reverse strand). Ensembl gene ENSG00000200867.
Homologues: Orthologues: chimpanzee 7SK (89% identical), mouse Gm54519 (52% identical). Paralogues in human: 7SK (77% identical), RN7SKP203 (76% identical), RN7SKP255 (74% identical), RN7SKP176 (73% identical), RN7SKP25 (73% identical), RN7SKP103 (73% identical), RN7SKP90 (73% identical), RN7SKP153 (73% identical), RN7SKP246 (73% identical), RN7SKP124 (72% identical), RN7SKP162 (72% identical), RN7SKP185 (72% identical), and 284 more.